MMP2 (matrix metallopeptidase 2)
Diseases named in the same sentence as MMP2 in open-access papers (continued):
Sharing a sentence is not in itself a finding about the gene and the disease.
endometriosis (continued). "A panel consisting of MMP-2, MMP-9, and MMP-9/neutrophil gealtinase-associated lipocalin was significantly elevated in a cohort of 33 women with endometriosis relative to expression in a group of 13 controls." (PMID 26240814, 2015). "Kidney-tonifying medicine has also been found to reduce matrix metalloproteinase-2 (MMP-2) expression in endometriosis (presumably by improving the local endocrine environment), so as to reduce the invasion of ectopic endometrium." (PMID 25792996, 2015). "In red and white endometriosis, there was a higher expression of MMP-2 in layer than in black homes." (PMID 24294950, 2013). "It was previously reported that eutopic uterine endometrium from endometriosis patients had higher MMP-2 and lower TIMP-2 expression levels compared with normal fertile women." (PMID 23855590, 2013). "Although the MMP-2 promoter lacks a canonical progesterone response element (PRE), the hormone inhibits MMP-2 expression and is part of treatment protocols in gynecological invasive pathologies, including endometriosis and endometrial hyperplasia." (PMID 19426551, 2009). "MMP-2 and -9 act as downstream biomarkers involved in the progression of endometriosis." (PMID 40565017, 2025). "The increased levels of MMP-1, MMP-2, and MMP-3 in endometriotic lesions observed in this study indicate that endometriosis may have a distinct metabolomic signature linked to cell cycle arrest and inflammation." (PMID 40834152, 2025). "Increased levels of MMP-1, MMP-2, and MMP-3 in endometriotic lesions indicate that endometriosis may have a unique metabolomic signature linked to cell cycle arrest and inflammation." (PMID 40834152, 2025). "Elevated MMP-2 expression in the ectopic endometrium may indicate the aggressive progression of endometriosis, highlighting the need for targeted therapies." (PMID 39768606, 2024). "Both MMP2 and MMP3 have been implicated in the pathogenesis of endometriosis." (PMID 35453712, 2022). "Moreover, high MMP-2 levels are correlated with advanced endometriosis, and few studies describe the clinical effectiveness of zinc supplementation." (PMID 34681755, 2021). "Furthermore, cisplatin combined with letrozole was found to inhibit angiogenesis in a rat model of endometriosis by altering MMP2 activity." (PMID 34827737, 2021). "Specifically, endometrial cells treated in vitro with DEHP exhibit cellular invasiveness and the activation of molecular pathways involved in the establishment of endometriosis and endometrial proliferation (MMP-2 and -9 activation, Erk phosphorylation, and p21-activated kinase expression)." (PMID 34227050, 2021). "Moreover, it has been reported that dehydrocostus lactone, isolated from Aucklandia lappa, inhibited the expression of MMP2 and MMP9 in endometriosis-associated macrophages (EAMs) and influenced the polarization of macrophages." (PMID 34827737, 2021). "The fibrinogen alpha chain is upregulated and affects MMP2 in endometriosis." (PMID 34827737, 2021). "Similarly, the inhibition of COX2 by celecoxib reduced MMP2 activity in an in vivo mouse model of endometriosis." (PMID 33919029, 2021). "Another study showed that MMP2 and TIMP2 were associated with advanced-stage endometriosis." (PMID 34827737, 2021). "Moreover, iron markedly increased EMT and MMP-2/-9 expression in endometriotic lesions in an endometriosis mouse model." (PMID 33121166, 2020). "However, we found only a few studies in which authors investigate MMP-2 expression in endometriosis." (PMID 33072202, 2020).
endometriosis (continued). "In order to demonstrate a role for MMP-2 in endometriosis, it has been found that women with endometriosis show increased MMP2 expression compared with healthy controls; meanwhile, the levels of the tissue inhibitors of metalloproteinase-2 (an inhibitor of MMP-2) mRNA were significantly lower." (PMID 32046116, 2020). "Furthermore, the concentration of MMP-2 has been shown to be significantly elevated in the serum and peritoneal fluid of women with endometriosis in comparison to healthy women." (PMID 30981279, 2019). "Wang and Ma evaluated the effects of estrogen and progestin on expression of MMP2 and tissue inhibitor of MMP2 in a nude mouse model of endometriosis and showed that estrogen can raise the expression level of MMP2 to promote ectopic implantation of endometrial tissue." (PMID 28280797, 2017). "The expression ratio of OPN and MMP2 to housekeeping gene in both recovered transplanted samples (endometriosis models A, B) was higher than the control 1 and control 2 (p=0.03) and these expression ratios in ectopic tissue in model B was higher than the model A (p=0.03)." (PMID 28280797, 2017). "Similarly, induction of endometriosis enhanced the levels of MMP-2 and MMP-9 in peritoneal fluid and cells in an in vivo study using BALB/c mice." (PMID 28264481, 2017). "In addition, miR-520g also induced endometriosis via upregulation of MMP2 expression, which is an indicator of tumor metastasis." (PMID 27049921, 2016). "Although studies have identified the involvement of different matrix metalloproteinases (MMPs) in endometriosis, no study has yet investigated the role of MMP-2 in endometriosis-associated angiogenesis." (PMID 27695098, 2016). "However, when the same sample was inoculated with selective inhibitor for MMP-2, angiogenic branching was significantly reduced in comparison to only endometriosis extract treatment." (PMID 27695098, 2016). "The endometrium requires hormone-dependent periodic remodeling and angiogenic responses for its proper functioning; thus attenuated MMP-2 activity might indicate abnormal cellular and angiogenic responses in the uterus of endometriosis patients." (PMID 27695098, 2016). "Moreover, MMP-2 expression in the peritoneal fluid of endometriosis patients was positively correlated with 17β-estradiol level, and negatively correlated with progesterone levels." (PMID 27695098, 2016). "The reduced expression of TIMP-2 indicated attenuated inhibition on MMP-2 activity, however it also suggested that limited TIMP-2 and increased MT1MMP expressions are associated with increased MMP-2 activation during the progression of endometriosis." (PMID 27695098, 2016). "In addition, increased MT1MMP and decreased tissue inhibitors of metalloproteinases (TIMP)-2 expressions were found in the late stages of endometriosis indicating more MMP-2 activation with disease progression." (PMID 27695098, 2016). "Finally, to understand the angiogenic potential of MMP-2 in endometriosis, chick chorioallantoic membrane (CAM) assay was performed." (PMID 27695098, 2016). "Administration with anti-mouse IL-10 neutralizing Abs or TGF-β receptor antagonist (SB431542) also limited the growth of endometriosis lesions and downregulated the expression of Ki67, MMP2 and Cox-2 by ESCs and endometrial glandular epithelial cells (EECs) in the endometriosis lesions." (PMID 25275597, 2014). "MMP-2 mRNA expression was significantly higher in epithelial cells prepared from the menstrual endometrium than from the other phases in the cycle in patients with endometriosis." (PMID 23626717, 2013). "Recently, it was demonstrated in mice that the treatment of 15-Epi-lipoxin A4 (LXA4) may inhibit the progression of endometriosis possibly by lowering the concentrations and the activities of MMP-2 and MMP-9." (PMID 20085636, 2010).
endometriosis (continued). "However, it has also been found in endometriosis and adenomyosis, with a suppressor role in the control of cell proliferation, inhibiting migration, and invasion and decreasing the expression of matrix metalloproteinase 2 (MMP2) via the Rac1/NF-kB signaling pathway." (PMID 38337827, 2024). "By this approach, MMP2 shows a prevalent epithelial glandular staining in healthy endometrium, while an intense, more diffuse staining in both the glandular and the stromal compartment may be highlighted in endometrium of patients suffering from endometriosis." (PMID 32325785, 2020). "Since endometriosis influences endometrium receptivity and MMP-9 responses, we explored whether women with endometriosis are predisposed to change in the activity of MMP-2 in eutopic endometrium." (PMID 27695098, 2016). "Moreover, advanced endometriosis is correlated with a higher MMP-2 expression." (PMID 26240814, 2015). "Matrix metalloproteinases (MMPs) activity, including MMP2 and MMP9, is elevated in the ectopic tissue of endometriosis." (PMID 40457415, 2025). "Resveratrol reduced MMP-2 and MMP-9 levels in the endometrium and blood of women with endometriosis." (PMID 40508002, 2025). "One study has shown an increase in MMP-2 and MMP-9 in the sites of endometriosis compared with the eutopic endometrium." (PMID 38255200, 2024). "Inflammatory mediators, such as cytokines and growth factors, can also stimulate the production of MMP-2, MMP-9, and TGF-β1 in endometriosis." (PMID 38398530, 2024). "Therefore, we may presume that KISS1, KISS1R, MMP-2, and MMP-9 can be used for the diagnostic, assessment of the progression of endometriosis and the effectiveness of treatment of this disease in women from 23 to 38 years old without endocrine system pathology and oncology diseases." (PMID 38255200, 2024). "The active forms of matrix metalloproteinase MMP-2 and MMP-9 are particularly important during the early stages of extragenital endometriosis development." (PMID 39768606, 2024). "The observed reduction of MMP-2 and MMP-9 expression in the endometriotic tissue therefore suggests a positive role of resveratrol in the reduction of endometriosis invasiveness." (PMID 38612425, 2024). "Since MMP-2 and MMP-9 can break down and inactivate KISS1, an increase of MMP activity in endometriosis can work through feedback to decrease KISS1 levels, additionally eliminating possible inhibiting effects of KISS1 on migration and invasion." (PMID 38255200, 2024). "MMP-2 and MMP-9 are involved in the invasion and dissemination of endometrial cells, which leads to the occurrence and development of endometriosis." (PMID 38398530, 2024). "The heightened activity of MMP-2 and MMP-9 plays a significant role in several important aspects of endometriosis as well." (PMID 38398530, 2024). "MMP-2 and MMP-9 genes express statistically significant increases in stages II, III, and IV of extragenital endometriosis." (PMID 38255200, 2024). "Active forms of MMP-2 and MMP-9 are particularly important at early stages of extragenital endometriosis development." (PMID 38255200, 2024). "This is consistent with findings that the MMP-2 and MMP-9 activity is increased in women with the eutopic endometrium compared to endometriosis." (PMID 38255200, 2024). "The aim of our study was to study KISS1/KISS1R, MMP-2, and MMP-9 gene expression and protein synthesis in endometriosis and compare them with the normal endometrium." (PMID 38255200, 2024). "MMP-2 and MMP-9 have been extensively studied in the scope of endometriosis, mainly because they are present at high levels in the peritoneal fluid of patients with endometriosis." (PMID 35164046, 2022). "Our data showed a higher expression of MMP-2 and MMP-9 genes in endometriosis cells (E-MenSCs) (7.6 and 5.8 fold), as compared with NE-MenSCs." (PMID 35059465, 2022). "It has also been shown that VEGF, MMP-2 and MMP-9 are significantly elevated in the serum of patients with endometriosis." (PMID 36386543, 2022).
endometriosis (continued). "MMP-2 activity promotes angiogenesis and neovascularisation that the role of MMP-2 through PGE2-mediated pathway for the promotion of angiogenesis in endometriosis." (PMID 36435808, 2022). "In the present study, the patients with endometriosis showed higher levels of TIMP1 and MMP2 in the peritoneal fluid, as compared to the controls." (PMID 34686725, 2021). "An animal study revealed naringenin potential against endometriosis by reducing expression of various endometriosis prognostic markers (TAK1, PAK1, VEGF, PCNA, MMP2, and MMP-9) in endometriotic lesions developed in rats." (PMID 33919512, 2021). "MMP2 and MMP9 can be regarded as the most typical downstream biomarkers in the progression of endometriosis." (PMID 34827737, 2021). "In conclusion, the authors emphasized the need for further research on the effect of resveratrol on MMP-2 and MMP-9 expression in women with endometriosis." (PMID 33919512, 2021). "Zn is known as an inhibitor of MMPs, and increased levels of MMP-2 and MMP-9 were found in women suffering from endometriosis." (PMID 34681755, 2021). "In the current study, we demonstrate that the expression of endometrium MMP-2 and MMP-9 are increased in patients with endometriosis." (PMID 33072202, 2020). "We also examined the possible correlation between MMP-2 and MMP-9 levels in eutopic and ectopic endometrium in patients with endometriosis." (PMID 33072202, 2020). "In fact, the levels of MMP-2 and MMP-9 were found to be higher in the peritoneal fluid of women with endometriosis compared to that of healthy patients." (PMID 33121166, 2020). "High levels of MMP-2 and MMP-9 and low levels of TIMP-1 were related with low production of mature oocytes and subsequent decreased quality of embryos in endometriosis patients who underwent in vitro fertilization (IVF)." (PMID 31037923, 2019). "MMP-2 and MMP-9 levels were shown to be higher in patients with endometriosis than in healthy controls." (PMID 30888523, 2019). "Matrix metalloproteinases (MMPs), especially the gelatinases MMP-2 and MMP-9, play a crucial role in the pathogenesis of endometriosis by enabling invasion." (PMID 30981279, 2019). "Previous studies have reported higher levels of MMP-2 expression and lower mRNA levels for TIMP-2 in eutopic tissues of endometriosis patients relative to the endometrium from control groups." (PMID 31037923, 2019). "Proteolytic enzymes, like gelatinases (MMP-2 and MMP-9), play an important role in the initial development of endometriosis through ECM degradation." (PMID 31037923, 2019). "The results showed that VEGF, MMP-2 and MMP-9 were elevated in the sera of the patients suffering from endometriosis." (PMID 31727934, 2019). "In summary, we observed that U. urealyticum infection increases inflammatory mediators, adhesion molecules, and MMP-2 expression in PMCs through TLR2 signaling and promotes endometriosis." (PMID 31636643, 2019). "We sought to assess the correlation between the expression of MMP-2 and MMP-9 and the PR-A/PR-B ratio in endometriosis." (PMID 31037923, 2019). "Among the various MMPs, gelatinases MMP-2 and MMP-9, which degrade the principal component of basement membranes, collagen IV, have been intensively investigated in the context of endometriosis." (PMID 28264481, 2017). "MMP-2 and MMP-9 are elevated in the peritoneal fluid of patients with endometriosis compared to healthy people." (PMID 28264481, 2017). "MMP-2 and MMP-9 have been found to be significantly increased in endometriosis patients versus controls." (PMID 26240814, 2015). "MMP-2 and MMP-9, by degrading extracellular cellular matrix and promoting the release of key factors, play a critical role in the pathogenesis of endometriosis." (PMID 23843796, 2013). "The aim of this study was to explore the effect of a traditional Chinese medicine (Xiaochaihu Tang, XCHT) on the expression of matrix metalloproteinase-2 (MMP-2) and MMP-9 in rats with endometriosis (EMs)." (PMID 24255667, 2013).
endometriosis (continued). "Several MMPs such as MMP1, MMP2, MMP 3, MMP10, MMP 11, and MMP 14 are identified as endometriosis-specific genes." (PMID 19055724, 2008). "In endometriosis, metal iron facilitates EMT and enhances the activities of MMP-2 and -9." (PMID 40565017, 2025). "Total MMP-2 activity was analyzed using gelatin zymography of tissue biopsy and peritoneal fluid lysates from women with and without endometriosis." (PMID 40834152, 2025). "Metformin treatment of endometriosis has been used, which decreases the expression levels of critical inflammatory and angiogenesis-related genes including VEGF, MMP2, and MMP9, while stimulating tissue inhibitors of metalloproteinase, endometrial stromal cells, and progesterone receptor expression." (PMID 40650261, 2025). "The increased levels of MMP-2 and MMP-3 in endometriotic lesions compared with those in the eutopic and control endometrium could be a distinct metabolomic signature in endometriosis, potentially resulting from cell cycle arrest." (PMID 40834152, 2025). "Significantly higher levels of plasma MMP2 (p = 0.008), MMP9 (p = 0.001), and TGF-β1 (p = 0.053) were determined in the CTRL group when compared with the SHAM group (day 0), supporting the successful induction of endometriosis in rats." (PMID 38398530, 2024). "It has been suggested that deviating levels of MMP-2, MMP-9, and TIMP could contribute to the development of endometriosis." (PMID 38255200, 2024). "Similarly, the relative level of MMP-2 mRNA expression increased statistically significantly by 2.9, 4.1, and 4.3-fold in the II, III, and IV stages of extragenital endometriosis, respectively, compared with the control." (PMID 38255200, 2024). "MMP-2 and MMP-9 are the key factors of endometriosis progression and pathogenesis." (PMID 38255200, 2024). "Also, other factors can influence the levels of MMP-2, MMP-9, and TGF-β1 in endometriosis, including estrogen and progesterone, which are the primary sex hormones." (PMID 38398530, 2024). "Moreover, the expression of MMP-2 and MMP-9 has been shown to be increased in women with endometriosis when compared to controls." (PMID 36901866, 2023). "AEBP1 and HOXB6, together with IGF-1, CYP11A1, MMP-2, CC2D2A, IER3, STX18, maybe staging markers for endometriosis." (PMID 36532015, 2022). "For example, compared with MSCs in women without endometriosis (normal MSCs), MSCs in endometriosis patients (endometriotic MSCs) express higher levels of Cyclin D1, Matrix metalloproteinases (MMP)-2, and MMP-9." (PMID 36358904, 2022). "Moreover, the increased expression and activity of MMPs such as MMP2, MMP3, and MMP9 has been reported in endometriosis." (PMID 36551177, 2022). "Aberrant regulation of MMPs such as MMP2, MMP3, and MMP9 has been reported in endometriosis." (PMID 35453712, 2022). "Also, it was demonstrated that the expression of MMP-2 and MMP-9 is overexpressed in the eutopic endometrium as well as the endometriotic lesions of patients with endometriosis." (PMID 35059465, 2022). "Further, an IL-34 neutralizing antibody could attenuate CSF1R/JAK3/STAT6 activation and down-regulate VEGF, MMP-2 and MMP-9, eventually leading to suppression of the development of endometriosis in vitro." (PMID 31727934, 2019). "Unsurprisingly, IL-34, VEGF, MMP-2 and MMP-9 were increased in the sera of the experimental endometriosis rats, which could be abrogated by STAT6 signaling blockage with AS1517499." (PMID 31727934, 2019). "In addition, the expression of matrix metalloproteinase (MMP)-2 and MMP-9 have been shown to be higher in women with endometriosis compared to healthy controls." (PMID 28264481, 2017). "Although several studies have reported presence of MMP-2 in endometriosis; no study has looked into MMP-2 activity during pathogenesis of endometriosis." (PMID 27695098, 2016). "Women with endometriosis showed decreased MMP-2 activity in eutopic endometrium as compared to women without endometriosis." (PMID 27695098, 2016).